EXOC2 (exocyst complex component 2)
Description:
Component of the exocyst complex involved in the docking of exocytic vesicles with fusion sites on the plasma membrane.
Synonyms: SEC5; SEC5L1; FLJ11026; NEDFACH; Sec5p
Tractability: Antibody: its Gene Ontology location is reachable by antibodies, with high confidence. PROTAC: ubiquitination databases record sites on it; its protein half-life has been measured.
Gene: Protein-coding gene on chromosome 6 (485,133 to 693,169, reverse strand). Ensembl gene ENSG00000112685.
Subcellular location: Midbody, Midbody ring
Subcellular location (Human Protein Atlas): Vesicles
Pathways (Reactome):
Metabolism of proteins: Insulin processing
Organelle biogenesis and maintenance: VxPx cargo-targeting to cilium
Vesicle-mediated transport: Translocation of SLC2A4 (GLUT4) to the plasma membrane
Gene Ontology:
Molecular function: protein binding; protein kinase binding; small GTPase binding; GTP-dependent protein binding
Biological process: Golgi to plasma membrane transport; regulation of entry of bacterium into host cell; exocytosis; membrane fission; mitotic cytokinesis
Cellular component: exocyst; membrane; cytosol; plasma membrane; cell periphery; Flemming body
Genetic constraint (gnomAD): Loss-of-function variants: 59 observed, 117.05 expected, observed/expected ratio (o/e) 0.5, 90% interval 0.41 to 0.63. The upper end of that interval is the gene's LOEUF score, 0.63, which puts it in group 2 of 6, group 1 being the genes least tolerant of losing a copy. Missense variants: 859 observed, 1,086.2 expected, observed/expected ratio (o/e) 0.79, 90% interval 0.75 to 0.84. Synonymous variants: 393 observed, 399.28 expected, observed/expected ratio (o/e) 0.98, 90% interval 0.9 to 1.07.
Gene-disease validity (ClinGen):
ClinGen rates the evidence that EXOC2 causes each of these diseases.
complex neurodevelopmental disorder (autosomal recessive): Limited. A disorder that involves more than one phenotype associated with the central nervous system, including but not limited to intellectual disability, autism, and seizures (epilepsy).
Homologues: Orthologues: chimpanzee EXOC2 (99% identical), macaque EXOC2 (99% identical), dog EXOC2 (96% identical), rat Exoc2 (94% identical), mouse Exoc2 (94% identical), guinea pig EXOC2 (93% identical), rabbit EXOC2 (91% identical), pig EXOC2 (87% identical), tropical clawed frog exoc2 (80% identical), zebrafish exoc2 (77% identical), Drosophila melanogaster Sec5 (34% identical), Caenorhabditis elegans sec-5 (27% identical).
Diseases named in the same sentence as EXOC2 in open-access papers:
EXOC2 is named in the same sentence as 27 diseases in open-access papers, as found by Europe PMC text mining. Sharing a sentence is not in itself a finding about the gene and the disease. The quoted sentences say what the papers report.
viral infections (5 papers, 2013 to 2025). "EXOC2 is also involved in immune responses against viral infection through the co-localisation with STING and subsequent stimulation of interferon genes." (PMID 33148325, 2020). "SEC5 (also known as EXOC2) is a component of the exocyst complex and is involved in tank-binding kinase 1 (TBK1)-dependent type I interferon innate immune responses against viral infections." (PMID 36313547, 2022).
developmental delay (2 papers, 2020 to 2023). "EXOC2 variants have been found in patients with developmental delay and brain abnormalities, suggesting a critical role for EXOC2 in neuronal health during development." (PMID 37085629, 2023). "Specifically, pathogenic variants of EXOC2 were associated with brain abnormalities including severe developmental delay, dysmorphism, poor motor skills and microcephaly." (PMID 33260776, 2020).
ciliopathies (1 paper, 2025). "Mutations or deletions in genes encoding exocyst proteins, including EXOC2, EXOC4, EXOC7, and EXOC8, have been associated with ciliopathies and neural developmental disorders." (PMID 40777261, 2025).
Crohn disease (1 paper, 2018). A gastrointestinal disorder characterized by chronic inflammation involving all layers of the intestinal wall, noncaseating granulomas affecting the intestinal wall and regional lymph nodes, and transmural fibrosis. "Another suggestive gene, EXOC2, is associated with innate immunity and has been shown to play a role in susceptibility to Crohn’s disease." (PMID 29293537, 2018).
glaucoma (1 paper, 2018). Increased pressure in the eyeball due to obstruction of the outflow of aqueous humor. "We also investigated 9 novel glaucoma-associated loci from UKB in GERA, and 6 of the novel loci replicated at Bonferroni significance (near IKZF2, CADM2, near DGKG, ANKH, EXOC2, and LMX1B)." (PMID 29891935, 2018).
nephrotic syndrome (1 paper, 2023). A collection of symptoms that include severe edema, proteinuria, and hypoalbuminemia; it is indicative of renal dysfunction. "Mutations in EXOC8 and EXOC2 are associated with neurodevelopmental disorders, and mutations in EXOC6B with skeletal abnormalities and mutations in EXOC4 have been associated with nephrotic syndrome." (PMID 36920342, 2023).
skin cancer (1 paper, 2008). "On the same chromosome, 145.8 kb centromeric from the IRF4 rs12203592, the SNP rs6918152 in the EXOC2 gene was associated with hair color (black to blond) in the initial GWAS, the NHS skin cancer controls, and the Australian samples." (PMID 18483556, 2008).
neurodevelopmental disorder (5 papers, 2022 to 2025). A behavioral and cognitive disorder with onset during the developmental period that involves impaired or aberrant development of intellectual, motor, or social functions. "For example, Exoc2, a subunit of the exocyst complex, is associated with neurodevelopmental disorder with dysmorphic facies and cerebellar hypoplasia (NEDFACH)." (PMID 38390945, 2024). "Consistent with this, pathogenic variants in EXOC2 cause a severe neurodevelopmental disorder with dysmorphic facies and cerebellar hypoplasia (MIM# 619306) leading to reduced exocytosis and defective Arl13B localization to the primary cilia in patient cells." (PMID 36150098, 2022). "Defects in the human homologues of yeast SEC5 (corresponding to human EXOC2), SEC6 (EXOC3L2), SEC8 (EXOC4), SEC15 (EXOC6B), EXO70 (EXOC7), EXO84 (EXOC8), and RHO3 (RALA) are associated with a variety of neurodegenerative and neurodevelopmental disorders." (PMID 39560727, 2024).
infection (4 papers, 2020 to 2025). The state of being infected such as from the introduction of a foreign agent such as serum, vaccine, antigenic substance or organism. "During infection, SopB mobilizes membrane reservoirs and recruits EXOC2 from RAB10+ membrane reservoirs to invasion sites via its catalytic activity." (PMID 38600106, 2024). "For example, the knockdown of EXOC2 (a.k.a Sec5) inhibited the infection of SARS-CoV-2." (PMID 41292918, 2025). "To test this, we examined the localization of EXOC2 and EXOC3 prior to STm infection." (PMID 38600106, 2024). "Here, we observed that EXOC3 but not EXOC2 recruitment is diminished during infection of ΔsopE2 mutant bacteria compared to WT STm." (PMID 38600106, 2024).
EXOC2 also shares sentences with these, for which no sentence is quoted: cancer (3 papers); tumor (3); melanoma (2); abortion (1); B cell lymphomas (1); basal cell carcinoma (1); breast carcinoma (1); Cerebellar hypoplasia (1); cyst (1); fungal infection (1); insulinoma (1); microcephaly (1); nevus (1); pancreatic tumor (1); rheumatoid arthritis (1); spontaneous abortion (1); squamous cell carcinoma (1); systemic candidiasis (1).